IL2 (interleukin 2)
Diseases named in the same sentence as IL2 in open-access papers (continued):
Sharing a sentence is not in itself a finding about the gene and the disease.
Arthritis (51 papers, 2005 to 2025). Inflammation of a joint. "Associations of T cell subsets with IL-2 level in chikungunya arthritis cases." (PMID 38507338, 2024). "In animal arthritis models, the levels of TNF-α, IL-2, and IL-10 were decreased by the HO-1 inducer cobalt protoporphyrin IX (CoPP), indicating that HO-1 deficiency causes chronic inflammatory conditions in arthritis." (PMID 25313362, 2014). "↑ lymphocyte proliferation and macrophage H2O2 productionPrevent the activation of immune cells induced by collagen-induced arthritis↑ Plasma levels of corticosterone, progesterone, and interleukin-2 (IL-2)." (PMID 41154214, 2025). "This study aims to observe the effects of low-dose IL-2 combined with TCZ on arthritis symptoms and immune cells in active RA patients, based on the good results of low-dose IL-2 combined with bDMARDs, excluding TCZ, reported in previous studies." (PMID 38711497, 2024). "Our study suggests in this cohort with continued mild to moderate clinical arthritis that IL-2 and IL-10 levels are unchanged over time." (PMID 38873035, 2024). "Administration of anti-CD44 antibodies inhibited inflammation in mouse models of inflammatory bowel disease, collagen- and proteoglycan-induced arthritis, cutaneous inflammation, and IL-2-induced vascular leak." (PMID 39095775, 2024). "The investigation into the use of IL2-based therapeutics to treat post-CHIKV arthritis yielded interesting results." (PMID 37147383, 2023). "Our aims were 1) to describe the role of IL2 in Treg expansion and corresponding arthritis severity in CHIKV arthritis and 2) to determine the role of IL2 therapy in treating CHIKV arthritis in a mouse model." (PMID 37147383, 2023). "In a rat model of arthritis induced by type II collagen and treated with DAPs, IL-1β, IL-2, IL-6, TNF-α, IFN-γ, and dihydroorotate dehydrogenase (DHO-DHase) were inhibited." (PMID 36235835, 2022). "We observed a significant delay in disease onset and ease in arthritis severity scores following injection of IL‐2 (1 × 105 IU/3 days) on Day 14 after CII/CFA immunization." (PMID 33098626, 2020). "We observed that the injection of IL‐2 significantly blocked the incidence rate of arthritis, and the injection of SP600125 almost completely blocked the role of JNK in vivo." (PMID 33098626, 2020). "We aimed to evaluate the role of IL2 and Tregs in septic arthritis using a well-established mouse model of haematogenously spred S. aureus arthritis." (PMID 32111171, 2020). "Compared with the control group, the expression of NF‐κB p65/P50 significantly decreased in the IL‐2 group, indicating that the phosphorylation of NF‐κB participated in the treatment of collagen‐induced arthritis by low dose of IL‐2." (PMID 33098626, 2020). "Sγc mediated impaired IL-2 response of T cells caused increased IL-17 production and worsening of EAE and arthritis symptoms." (PMID 31110501, 2019). "Compared with phosphate-buffered saline (PBS) and NC siRNA control groups, administration of IL-2/15Rβ siRNA nanoparticles significantly reduced clinical signs of arthritis, as assessed by paw swelling and arthritis scores." (PMID 24223832, 2013). "In this study we assessed the therapeutic efficiency of IL-2/15Rβ siRNA for systemic delivery in experimental arthritis." (PMID 24223832, 2013). "The main objective of the study was to define the relationship between CHIKV arthritis disease severity, IL-2, and T-cell subsets in order to identify if arthritis therapies targeting enhanced regulatory T-cell activity may provide benefit." (PMID 38507338, 2024). "Deficient IL2 levels in CHIKV arthritis lead to a lack of Treg expansion and activation, allowing T effector cells to expand unregulated and leading to increased local inflammation." (PMID 37147383, 2023).
Arthritis (continued). "We fabricated the model of arthritis in mice, and then low‐dose IL‐2 was injected at a fixed time point to observe the changes of related vascular and organ pathology, inflammatory factors, and signal pathway proteins, which were verified by statistical analysis." (PMID 33098626, 2020). "In addition, to determine the activation of JNK in vivo, SP600125 (30 mg/kg iv) was injected on the same day when IL‐2 was injected into the arthritis model." (PMID 33098626, 2020). "Likewise, the relevance of the observed increase in B cell frequencies after rAAV-induced IL2 production is unclear, but the contribution of B cells to host’s defenses in S. aureus arthritis is thought to be limited." (PMID 32111171, 2020). "An expanded Treg compartment at bacterial inoculation and persistent IL2 release during the course of S. aureus arthritis reduced the systemic inflammatory response and led to an increase in bacterial clearance 10 days after bacterial inoculation, with no adverse effects on mortality or morbidity." (PMID 32111171, 2020). "Down regulation of immune responses via local production of ROS has been identified as important mechanism for prevention of an autoimmune response in arthritis and can be observed at the cellular level in macrophages as responsible for suppression of IL-2 production by T cells." (PMID 21079804, 2010). "Indeed, stratification of CII-specific T cells showed that both B22a1+ and B22a1- T cells mounted an IFNγ and IL-2 response that was maintained in the draining lymph node from day 10 post immunization and throughout the development of clinical arthritis." (PMID 20682070, 2010). "The efficacy produced by CP-690550 in the rodent models of arthritis may result from its ability to affect signaling of a number of cytokines including IL-2, -7, -15 and -21 as a consequence of JAK3 inhibition." (PMID 18234077, 2008). "Moreover, IL-17a and IL-2 plasma levels were notably elevated in IL-37atg, IL-1R8-/- mice (Figure A4A,B) compared with IL-37atg mice, indicating that IL-1R8 is essential for IL-37a-mediated suppression of arthritis and inflammatory responses." (PMID 39684587, 2024). "A mouse model for post-CHIKV arthritis was used to test the effects of recombinant IL2 (rIL2), an anti-IL2 monoclonal antibody (mAb), and the complex on tarsal joint inflammation, peripheral IL2 levels, Tregs, CD4 + effector T cells (Teff), and histological disease scoring." (PMID 37147383, 2023). "Could IL2 therefore be a treatment option in patients with S. aureus arthritis?" (PMID 32111171, 2020). "It is expressed in high levels in Th1 effector memory cells in inflamed joints and limits the expression of interferon-γ, IL-2, and TNF-α and ameliorates Th1-mediated immunopathology in antigen-induced arthritis." (PMID 40761796, 2025). "Adoptive transfer of adequate ILC2s to arthritis models, in which the isolated cells were expanded in vitro through stimulation using cytokines such as IL-2, IL-7, IL-25, IL-33, and TSLP, mitigated experimental arthritis." (PMID 35163028, 2022). "Concerning arthritis development, both PBS-or IL-2-treated B27-rats developed clinical joint inflammation during the observation period that was not significantly different between both groups." (PMID 34271972, 2021). "It is the first time for us to prove that low dose IL‐2 can inhibit osteoclast formation in collagen‐induced arthritis through the JNK dependent pathway, which will provide the angle and theoretical basis for future immunotherapy of IL‐2." (PMID 33098626, 2020). "Despite these successes, little is known of how the presence of low-dose IL2 and the consequent expansion of Tregs could affect beneficial effector immune responses when patients receiving the treatment develop acute bacterial infections, such as S. aureus arthritis." (PMID 32111171, 2020). "Large amounts of TNF-α and IFN-γ and small amounts of IL-2 and IL-6 were produced by splenocytes from mice with GPI-induced arthritis." (PMID 18534002, 2008).
Arthritis (continued). "In addition to improvements in arthritis, we evaluated CD4+T lymphocyte levels in patients treated with IL-2 and IL-2+TCZ after the corresponding regimen." (PMID 38711497, 2024). "Our preliminary data suggest that decreases in the cytokine interleukin-2 (IL2) during the acute stage of infection and the resulting alteration of regulatory T cell (Treg) function may play a role in CHIKV arthritis pathogenesis." (PMID 37147383, 2023). "Our preliminary data suggest that decreases in interleukin-2 (IL2) levels and regulatory T cell (Treg) function may play a role in CHIKV arthritis pathogenesis." (PMID 37147383, 2023). "Male mice with higher arthritis activity at 21 weeks had elevated serum levels of multiple cytokines compared to less arthritic females including GM-CSF, IFN-γ, IL-1β, IL-2, IL-12, and IL-17, as well as the growth factor FGF-basic, which correlated with higher arthritic scores." (PMID 33033318, 2020). "Taken together, these results suggest that Tregs are protective in S. aureus arthritis, but the effect obtained by enhanced IL2 production is not solely mediated by Tregs." (PMID 32111171, 2020). "On the one hand, in the early stage of arthritis, B cells, served as antigen-presenting cells, could present antigens to CD4 + T cells, and activate CD4+T cells to secrete IL-2 and IFN-γ in the synovial membrane." (PMID 32066378, 2020). "In summary, the anti-CII antibody, IL-2, IL-17, and IFNγ data do not provide a possible mechanism for the accelerated arthritis observed in this study." (PMID 22537858, 2012). "The results of this study showed that low-dose IL-2 combined with TCZ treatment could safely and effectively reduce arthritis symptoms in RA patients, promote the more stable proliferation of Tregs, and reduce the proliferation of Th2, Th17, and Th17/Treg caused by IL-2 treatment alone." (PMID 38711497, 2024). "Lymph node cells were isolated from model rats and administered with DAPs, and it was found that the expression levels of IL-1β, IL-2, IL-6, TNF-α and IFN-γ were significantly reduced, while the acceleration of arthritis severity could be attributed to the elevation of these factors." (PMID 36235835, 2022). "To determine whether the beneficial effects in S. aureus arthritis were due to Tregs or other IL2-mediated effects, we adoptively transferred CD4+CD25+ Tregs and found a clear, although not statistically significant, tendency to a reduction of both the clinical arthritis and bone erosion." (PMID 32111171, 2020). "This reflects the pleiotropic effects of IL-2 and the importance of identifying the optimal dose of low-dose IL-2 therapy in human trials of CHIKV arthritis to boost Tregs and Treg/Teff ratios without enhancing Teff cells." (PMID 38507338, 2024). "The levels of IL-2, IL-12p40, IL-12p70, and IL-15, as well as those of IL-10 and IL-13, did not increase in the setting of CFA-induced arthritis." (PMID 36293292, 2022). "Compared to SNS-gp130flox/flox mice SNS-gp130−/− mice showed significantly weaker initial swelling, reduced serum concentrations of CGRP, IL-6, and IL-2, no inflammation-evoked upregulation of CGRP in sensory neurons, but similar histopathological arthritis scores during AIA." (PMID 26590032, 2015).
gastric cancer (48 papers, 1993 to 2025). A primary or metastatic malignant neoplasm involving the stomach. "For gastric cancer, the presence of various polymorphisms for genes coding IL-2, which is associated with poor prognosis in gastric cancer patients, might provide a therapeutic target to inhibit gastric cancer progression." (PMID 35860357, 2022). "Through amplification of these effector cells, IL-2 enhances the detection and destruction of stomach cancer cells." (PMID 40309351, 2025). "These discoveries underscore the promise of IL-2 in rethinking gastric cancer therapy by harnessing its powerful immunostimulatory action with lower safety hazards." (PMID 40309351, 2025). "Various clinical studies have also indicated that IL-2 administration generates immune-mediated tumor regression in patients with gastric cancers." (PMID 40309351, 2025). "In‐vivo immunomodulatory effect on gastric cancer rats: Promotes splenocyte proliferation and improves anti‐inflammatory cytokines (IL‐2, IL‐4, and IL‐10) secretion." (PMID 41211514, 2025). "In accordance with our studies, adoptive transfer of ex vivo IL-2-activated NK cells combined with anti-PD-1 resulted in tumor growth inhibition in a xenograft gastric cancer model." (PMID 37197660, 2023). "IL-2 is primarily secreted by T cells, and our study observed a decrease in the total lymphocyte count among gastric cancer patients." (PMID 38022654, 2023). "IL-2 and IL-17 have opposite roles in the development of breast and gastric cancers and, therefore, we postulated that γδ T cells have distinct functions in different malignancies." (PMID 35493488, 2022). "For intestinal gastric cancer, low expression of IL-2 and IL-17 indicated a promising prognosis, whereas for diffuse and mixed gastric cancers, the expression of these cytokines did not significantly affect survival." (PMID 35493488, 2022). "The analysis of the expression of IL-2 in different subtypes of gastric cancer showed that low expression of IL-2 indicated a better prognosis in both intestinal and diffuse patients than high expression levels did." (PMID 35493488, 2022). "Our results also showed that the median survival of patients with gastric cancer who had low and high expression levels of IL-2 was 35.4 and 22 months, respectively (HR = 1.58, p < 0.001)." (PMID 35493488, 2022). "IL-2 and IL-17 are the two most important cytokines related to γδ T cells; therefore, we investigated their influence on breast and gastric cancers." (PMID 35493488, 2022). "Herein, we aimed to demonstrate the cytotoxic effects of a polytherapy consisting of ex vivo expanded IL-2-activated NK cells combined with human anti-PD-1 antibody as an important checkpoint molecule in a xenograft gastric cancer mouse model." (PMID 34588986, 2021). "We indicated that the adoptive transfer of ex vivo IL-2-activated NK cells combined with anti-PD-1 resulted in tumor growth inhibition in a xenograft gastric cancer model." (PMID 34588986, 2021). "γδ T cells were directly isolated from the peripheral blood of gastric cancer patients (defined as peripheral-derived γδ T cells) and cultured with irradiated autologous PBMCs in the presence of IL-2 and IL-15." (PMID 24741609, 2014). "IL-2 function seems to contribute considerably to the operation-induced immunosuppression in gastric cancer patients and preoperative treatment with IL-2 had been promising." (PMID 23033982, 2012). "We have investigated locoregional immunotherapy for malignant effusion, and have previously reported the clinical efficacy of the combined administration of OK-432 plus the T-cell growth factor interleukin-2 (IL-2) in gastric cancer patients." (PMID 14612896, 2003). "Gastric carcinomas have been shown to express eosinophil chemotactic cytokines including IL-2, IL-5 and GM–CSF and expression of GM–CSF appears to be specific for signet ring carcinoma cells." (PMID 11875724, 2002).
gastric cancer (continued). "This is consistent with the results of previous studies that added GLP that 400 mg/kg GLP reduced serum levels of IL-1β and IL-6 in diabetic rats, and 800 mg/kg GLP reduced serum IL-6 and TNF-α levels and increased serum IL-2, IL-4, and IL-10 levels in rats with gastric cancer." (PMID 39457856, 2024). "IL-2 helps NK cells restore Herceptin-mediated ADCC damage in gastric cancer patients." (PMID 39309440, 2024). "We demonstrate that CC-3 induces profound T cell reactivity against various pancreatic, hepatic and gastric cancer cell lines as revealed by analysis of activation, degranulation and secretion of IL2, IFNγ as well as perforin, resulting in potent target cell lysis." (PMID 37122707, 2023). "Moreover, the serum IL-6 and TNFα levels were decreased, and the serum IL-2, IL-4 and IL-10 levels were increased in gastric cancer mice after tea polysaccharides treatment." (PMID 36505461, 2022). "Moreover, the scFv and an IL-2 fusion protein of scFv-IL2 CAR T cells enhanced antitumor activity against gastric cancer cells." (PMID 36341440, 2022). "In MNNG gastric cancer rat model, administration of 50, 100 or 150 mg/kg body weight of lycopene caused an increment in antioxidant enzymes as expected (SOD, CAT, GSH-Px) and increment in cytokines (IL-2, IL-4, IL-10, TNF-α) and antibodies (IgG, IgA, IgM)." (PMID 34202203, 2021). "The anti-inflammatory effects of FFKSIL may be related to IgA, IgM, IgG, IL-6 and TNF-α production and IL-2, IL-4 and IL-10 reduction in gastric cancer rats." (PMID 22728348, 2012). "Moreover, although PMA activates caspase-3 through the PKC signaling pathway and this leads ultimately to apoptosis in a gastric cancer cell line, caspases also play a central role in T lymphocyte activation as well as in IL-2 release." (PMID 19046417, 2008). "This efficacy seemed better than that in gastric cancer patients, in which the earlier study reported that positive clinical responses were obtained in 60 and 81% when treated with OK-432 alone and with OK-423 plus IL-2, respectively." (PMID 14612896, 2003). "H19 is overexpressed in gastric cancer (GC) cells and contributes to immune escape from GC cells by decreasing immune cell activity and IL-2 expression through the miR-519d-3p/LDHA/lactate axis." (PMID 38715092, 2024). "However, IL-2 and IL-17 played a dinstinct role in gastric cancer prognosis." (PMID 35493488, 2022). "Therefore, the combination approach of ex vivo expanded IL-2-activated NK cell and PD-1 blockade is promising, and its effectiveness could be evaluated in randomized clinical trials for gastric cancer." (PMID 34588986, 2021). "We found MK2 expression to be linked to gastric cancer metastasis and nine significant cytokine associations, including MK2-dowstream cytokines, IL-1β, IL-6, and TNFα along with other previously unrecognized cytokines linked to MK2; G-CSF, GM-CSF, Mip-1β, IFN-α, MCP-1, and IL-2." (PMID 32216812, 2020). "In addition, a human gastric carcinoma cell line HR, transduced with the IL-2 gene, could secrete sufficient quantities of bioactive IL-2." (PMID 30719024, 2018). "In patients with gastric cancer at stages I, II, and III of the disease, there is an increase in such proinflammatory cytokines as TNF-α, IL-2, IL-8, TNF-β, IL-17A, and IL-6, as well as a decrease in IFNγ." (PMID 40806737, 2025). "In another study, human gastric cancer patient tumour MDSCs suppressed T cells ex vivo via IL-10, resulting in a decrease in CD4+ T cell production of IL-2 and IFNγ consistent with impaired effector function." (PMID 38464388, 2024). "With stable suppression of GLIPR1 in HGC27, both CAR-T cells increased cytotoxicity against cancer cells and cytokine production of IFN-γ and IL-2, suggesting CAR-T cells displayed better functions in gastric cancer with GLIPR1 knockdown." (PMID 38368374, 2024). "We found that production of the cytokines tested (IL-2, IL-4, IL-6, IL-10, IFN-γ) were up-regulated after exposure to gastric cancer derived exosomes." (PMID 32901082, 2020).